TCF4 (transcription factor 4)
Diseases named in the same sentence as TCF4 in open-access papers (continued):
Sharing a sentence is not in itself a finding about the gene and the disease.
breast cancer (continued). "On the other hand, in patients expressing low levels of OPN, Tcf-4 predicted a better survival, implying that in a low OPN background, Tcf-4 may act as a tumour suppressor in breast cancer patients." (PMID 21772333, 2011). "Others have also shown that Tcf-4 has a tumour suppressor function in breast cancer." (PMID 21772333, 2011). "Moreover, we identified that TCF4 was a direct target of miR-591 in breast cancer." (PMID 31049030, 2019). "Moreover, we identified that TCF4 was a target of miR-591 in breast cancer." (PMID 31049030, 2019). "Hence, we have emphasized that p68 upregulation by β-catenin/TCF4 may be one of the major contributing factors in breast cancer progression." (PMID 25499975, 2014). "Some of the alterations identified are drivers of different tumors and for VM formation: S1PR1 (breast cancer), PDGFRB, TIE-1 (melanoma), LOXL2 (hepatocellular carcinoma) and interestingly TCF-4." (PMID 36797281, 2023). "Our previous study showed that β-catenin translocated into the nucleus to form a transcription complex with TCF4 and LEF1, which then promotes FMOD transcription, subsequently leading to breast cancer cell migration and invasion." (PMID 36986805, 2023). "In summary, we suggest that LEF1, TCF3,TCF4, and TCF7 have the potential to bebiomarkers in breast cancer clinics." (PMID 38100720, 2023). "In our study, FGFR4 phosphorylated GSK-3β to activate β-catenin/TCF-4 signaling and drive anti-HER2 resistance in breast cancer." (PMID 35562334, 2022). "In breast cancer, Epsin 3 (EPN3) can enhance E-cadherin endocytosis, activate β-catenin/TCF4-mediated EMT and promote the autocrine loop mediated by TGFβ, and ultimately promote metastasis of breast cancer cell." (PMID 34034721, 2021). "In ER+ breast cancer, S100A7 limits the proliferation and motility of tumor cells by downregulating the β-catenin/TCF4 pathway." (PMID 32728097, 2020). "High expression of TCF4 results in OPN promoter activity and protein expression in rat mammary carcinoma cells, and TCF4 can target repressors or activators of metabolic progression by regulating OPN expression via Wnt restoration." (PMID 32819387, 2020). "We find for the first time that in breast cancer cells FMOD expression is regulated positively by the Wnt/β-catenin signaling pathway, and FMOD is transcribed by the β-catenin/TCF4/LEF1 transcription complex which binds to the FMOD promoter at specific sites." (PMID 31824307, 2019). "Using lentivirus-mediated shRNA targeted for β-catenin, TCF4, and LEF1, we investigated the relation between endogenous β-catenin, TCF4, LEF1, ERK1/2 activity, and breast cancer cell migration and invasion." (PMID 31824307, 2019). "MicroRNA-100 suppresses the migration and invasion of breast cancer cells by targeting FZD-8 and inhibiting T-cell factor-4 (TCF-4) expression." (PMID 31049030, 2019). "Transwell experiments showed a dramatic inhibition of cell migration and invasion due to the reduction of β-catenin, TCF4, and LEF1 in the breast cancer cells." (PMID 31824307, 2019). "Stimulation of Wnt-signaling is predicted to activate the canonical Wnt responsive gene CyclinD1, which promotes breast cancer proliferation as well as LEF1 and TCF4, which are transcriptional mediators of the Wnt pathway." (PMID 27738322, 2016). "Filtering specifically for breast cancer datasets that included the recurrence risk during the first year following treatment, we found significant correlations between recurrence and the expression of negative (GSK3β) or positive (TCF4) regulators of Wnt/β-catenin signaling." (PMID 26202299, 2015). "Most importantly, Tcf-4 mRNA expression was correlated with better survival, while OPN mRNA expression was correlated with poorer survival in breast cancer patients." (PMID 21772333, 2011).
breast cancer (continued). "Immunohistochemical staining should be performed to study the protein expression, instead of mRNA expression, of Tcf-4 and OPN in a large human breast cancer patient cohort to confirm the correlations between OPN, Tcf-4 and patient survival time." (PMID 21772333, 2011). "We also studied breast cancer cell lines (AU565 and SK-BR3-3) because β-catenin/TCF4 is highly active in breast cancers." (PMID 20459822, 2010). "USP10 stimulates proliferation in ER-α-positive breast cancer cells and ER-α-negative breast cancer cells by enhancing the stability of TCF4 protein." (PMID 41294885, 2025). "However, a previous study showed that treatment of OE inhibits the upregulation of SMAD4 and SNAIL2 (Slug), TCF4, VIM (Vimentin), FN (fibronectin) and SERPINE1 genes in a breast cancer cell line and MDCK cells." (PMID 29940929, 2018). "The TCF4 signaling pathway is known to be a major regulator of CSC phenotype in colon and breast cancer and could be one of the mechanisms involved in HS06 action." (PMID 27705927, 2016). "Concordantly, the expression levels of multiple downstream targets of Wnt/β-catenin signaling, namely cyclin D1, c-MYC, TCF4 and LEF1, and nuclear β-catenin, were increased in the miR-1229–overexpressing breast cancer cells but decreased in the miR-1229–silenced breast cancer cells." (PMID 26992223, 2016). "As expected, the β-catenin/TCF4 activity and the expression levels of eight classically recognized Wnt/β-catenin target genes were significantly increased in the TBLR1 overexpressing breast cancer cells, but decreased in the TBLR1 silencing cells." (PMID 25341494, 2014). "GLCE is another a multiregulated gene, where GLCE expression in breast cancer is controlled through complex molecular mechanisms, including at least chromatin structure, TCF4/b-catenin complex, and microRNA-218, but not GLCE promoter methylation 14–17." (PMID 24403231, 2013). "Similarly, we observed that TN breast cancer cell lines (HCC38, HCC1143 and SUM149) with very high expression of beta-catenin also showed appreciable levels of TCF4 protein expression." (PMID 24143235, 2013). "As we have previously shown that osteopontin (OPN) is a downstream target of Tcf-4 in a rat breast epithelial cell line Rama37, the aim of the present study was to investigate how the Tcf-4/OPN link is regulated in human breast cancer and modulates human breast cancer progression." (PMID 21772333, 2011). "Investigation of the expression levels and their roles in Tcf-4 overexpressing MCF10AT or Tcf-4 knockdown MDA MB 231 cells may provide new mechanistic insights, in addition to OPN, on Wnt-mediated breast cancer progression." (PMID 21772333, 2011). "The mRNA expression of Tcf-4 and OPN, and survival of breast cancer patients were correlated." (PMID 21772333, 2011). "We also found that OPN was positively regulated by Wnt signalling in invasive breast cancer cell line MDA MB 231 and that Tcf-4 activation of OPN transcription might be dependent on Wnt signalling activity." (PMID 21772333, 2011). "Our results suggest that Tcf-4 can act as a repressor or activator of breast cancer progression by regulating OPN expression in a Wnt-dependent manner and that Tcf-4 and OPN together may be a novel prognostic indicator for breast cancer progression." (PMID 21772333, 2011). "The reasons for the paradoxical results obtained on the role of Tcf-4 in breast cancer progression are not clear." (PMID 21772333, 2011). "Furthermore, we demonstrated that miR-591 could regulate cell proliferation and invasion by targeting TCF4 and inhibited the TCF4 and Hippo-YAP signaling, which may function as a potential target of breast cancer treatment." (PMID 31049030, 2019). "Likewise, LiCl enhanced breast cancer cell motility; but the enhancement could be eliminated by knocking down FMOD, or individual components of the β-cat/TCF4/LEF1 transcriptional complex, or by inhibiting HDAC6 with Trichostatin A (TSA)." (PMID 31824307, 2019).
breast cancer (continued). "In conclusion, our results suggest that Tcf-4-regulated OPN expression and cell invasion may be dependent on Wnt signalling activity and that Tcf-4 and OPN, when considered together, may be a novel prognostic indicator in breast cancer." (PMID 21772333, 2011). "In addition, β-catenin and transcription factor 4 (TCF4) can bind to the promoter of the DDX5 gene to stimulate the expression of DDX5, which in turn promotes the transcription of the β-catenin-dependent TCF4 gene, forming a positive feedback loop to promote breast cancer progression." (PMID 35992805, 2022). "Filtering specifically for breast cancer datasets that included prognostic stages (categories) based on the size of the tumor and extent of metastasis, we found correlations between cancer stage and the expression of negative (GSK3β) or positive (TCF4) regulators of Wnt/β-catenin signaling." (PMID 26202299, 2015). "We also observed a higher level of protein expression for TCF4, DVL, and Axin in most of the TN breast cancer cell lines tested as compared to the non-TN breast cancer cell lines." (PMID 24143235, 2013).
Fuchs endothelial corneal dystrophy (50 papers, 2011 to 2026). Fuchs endothelial corneal dystrophy (FECD) is the most frequent form of posterior corneal dystrophy (see this term) and is characterized by excrescences on a thickened Descemet membrane (corneal guttae), generalized corneal edema, with gradually decreased visual acuity. "Fuchs endothelial corneal dystrophy (FECD) is frequently associated with trinucleotide repeat (TNR) expansion in the TCF4 gene intron." (PMID 40465262, 2025). "Variants in TCF4 are associated with Fuchs Endothelial Corneal Dystrophy (OMIM#613267,) a common autosomal dominant degenerative disorder with an incidence of nearly 5% of people over 40 years old living in the United States." (PMID 36701310, 2023). "Several mouse models have been developed to study corneal diseases, such as those with mutations in the transcription factor 4 (TCF4) gene for Fuchs' endothelial corneal dystrophy and mutations in the visual system homeobox 1 (VSX1) gene for keratoconus." (PMID 37642632, 2023). "Fuchs’ endothelial corneal dystrophy (FECD) is an RNA-mediated disease caused by a trinucleotide CTG expansion in an intron within the TCF4 gene." (PMID 32463444, 2020). "In addition, TCF4 showed a significant association with endothelial corneal dystrophy and abnormal retina morphology in vitro system and early adult mice." (PMID 38632618, 2024). "Similarly, TCF4, that encodes transcription factor 4, is a major risk factor for Fuchs endothelial corneal dystrophy, a corneal disease leading to visual impairment and blindness, and owing, notably, to an excessive accumulation of ECM51." (PMID 29235454, 2017). "In addition to PTHS, TCF4 is associated with several other human diseases such as schizophrenia, Fuchs' corneal endothelial dystrophy and primary sclerosing cholangitis." (PMID 26621827, 2015). "Expansion of CTG trinucleotide repeats (TNR) in the transcription factor 4 (TCF4) gene is highly associated with Fuchs Endothelial Corneal Dystrophy (FECD)." (PMID 34855896, 2021). "Amplification of a CAG trinucleotide motif (CTG18.1) within the TCF4 gene has been strongly associated with Fuchs Endothelial Corneal Dystrophy (FECD)." (PMID 31276570, 2019). "Trinucleotide repeat expansion in CTG18.1, in intron 2 of TCF4 (MIM *602272, #613267), is the main cause of Fuchs endothelial corneal dystrophy (FECD), accounting for around 75% of cases in Caucasians." (PMID 40720054, 2025). "Interestingly, a genome-wide association study (GWAS) revealed the presence of common polymorphisms near the TCF4 gene, establishing a clear link between these variants and an elevated risk of developing Fuchs endothelial corneal dystrophy (FECD)." (PMID 41160897, 2025). "Fuchs endothelial corneal dystrophy (FECD), the non-coding CTG repeat expansion in the TCF4 gene, causes RNA aggregation, triggering cell death in corneal endothelial cells through the activation of the unfolded protein response." (PMID 40282366, 2025). "The CRF loci analyzed here overlap 36 reported keratoconus risk loci, two of which are also Fuchs' endothelial corneal dystrophy (FECD) risk loci, and an additional FECD risk locus, TCF4." (PMID 37621707, 2023). "In this review, we first summarized the mutations of COL8A2, TCF4, TCF8, SLC4A11 and AGBL1 genes in Fuchs endothelial corneal dystrophy." (PMID 34130750, 2021). "The aims of this study were to use an isogenic cell model system to investigate the proteomic consequences of TCF4 trinucleotide repeat expansion in Fuchs endothelial corneal dystrophy (FECD) and to identify potential molecular pathways contributing to disease pathogenesis." (PMID 41865104, 2026). "A multi-ancestry GWAS meta-analysis of Fuchs endothelial corneal dystrophy identifies eight novel loci, including low-frequency missense variants in laminin genes LAMA5 and LAMB1, and phenome-wide scans uncover pleiotropy with renal traits at TCF4." (PMID 38582945, 2024).
Fuchs endothelial corneal dystrophy (continued). "Fuchs endothelial corneal dystrophy (FECD) leads to vision loss and is the most common repeat expansion-mediated disease characterised to date; most individuals with FECD harbour a non-coding CTG repeat expansion within the gene TCF4." (PMID 38713708, 2024). "The E-protein TCF4 (also called E2-2 and ITF2), which is a class I basic helix-loop-helix (bHLH) transcription factor, is involved in the pathogenesis of Fuchs’ endothelial corneal dystrophy, primary sclerosing cholangitis, Pitt–Hopkins syndrome, and several types of malignant tumours." (PMID 35406121, 2022). "After exclusion of the TCF4 index SNP, the GRS was still significantly associated with proteinuria, hyperlipidemia codes, gout, and hypertension with nearly identical ORs, but the association with Fuchs’ dystrophy disappeared (p = 0.2)." (PMID 31511532, 2019). "According to the latest research, Fuchs endothelial corneal dystrophy (FECD), strongly associated with expansion of the CTG18.1 locus in the transcription factor 4 gene, represents one of the most common trinucleotide repeat disorders." (PMID 36773096, 2023). "Up to 80% of Fuchs endothelial corneal dystrophy (FECD) patients have an expansion of 50 or more CTGs in the third intron of TCF4 (termed CTG18.1)." (PMID 36478959, 2022). "Late-onset Fuchs endothelial corneal dystrophy (FECD) is a disease affecting the corneal endothelium (CE), associated with a cytosine-thymine-guanine repeat expansion at the CTG18.1 locus in the transcription factor 4 (TCF4) gene." (PMID 36773096, 2023). "Fuchs Endothelial Corneal Dystrophy (FECD) is a late onset eye disease associated with an expanded trinucleotide repeat (TNR) in the TCF4 gene and a lack of other systemic findings." (PMID 34855896, 2021). "RNA toxicity from CTG trinucleotide repeat (TNR) expansion within noncoding DNA of the transcription factor 4 (TCF4) and DM1 protein kinase (DMPK) genes has been described in Fuchs' endothelial corneal dystrophy (FECD) and myotonic dystrophy, type 1 (DM1), respectively." (PMID 30025114, 2018). "This study evaluated the dysregulation of TCF4 isoforms and differential exon usage (DEU) in corneal endothelial cells (CECs) of Fuchs endothelial corneal dystrophy (FECD) with or without trinucleotide repeat (TNR) expansion in the intron region of the TCF4 gene." (PMID 38884552, 2024). "Similarly, variants in ZEB1, COL8A2, TCF4, FEN1, AGBL1, and LOXHD1 all cause Fuchs endothelial corneal dystrophy (FECD), while the age of onset may vary." (PMID 31555324, 2019). "The authors suggest that TCF4 may be an enzymatic target of AGBL1 and this interaction could potentially explain the development of Fuchs endothelial corneal dystrophy (FECD)." (PMID 38340174, 2024). "Distribution of significantly differentially expressed genes between module pairs in Fuchs’ endothelial corneal dystrophy (FECD) co-expression networks with (RE+) and without (RE-) the TCF4 CTG18.1 expansion." (PMID 40961119, 2025). "Shared modules of gene co-expression networks in Fuchs’ endothelial corneal dystrophy (FECD) patients with (RE+) and without (RE-) the TCF4 CTG18.1 expansion." (PMID 38096202, 2023).
Intellectual disability (47 papers, 2011 to 2026). "Associations with intellectual disability include rs78294462 in TCF4, rs376456 and rs1009136 in MAU2, and rs7200247 in GLG1." (PMID 40282399, 2025). "Heterozygous mutations of TCF4 in humans cause Pitt–Hopkins syndrome, a neurodevelopmental disease associated with intellectual disability and brain malformations." (PMID 40155049, 2025). "Mutations in the TCF4 gene cause Pitt–Hopkins syndrome, a rare neurological disorder characterized by developmental delay and intellectual disability." (PMID 37408271, 2023). "Pathogenic variant of TCF4 has been revealed to be related to Pitt–Hopkins Syndrome which is characterized by severe intellectual disability, seizures, and stereotypic movements." (PMID 35611576, 2022). "In humans, mutations in the 5′ region of TCF4 gene, which affect only the longer isoforms, lead to mild–moderate intellectual disability." (PMID 36407762, 2022). "Similar to TCF4, these interactors are often associated with neurodevelopmental disorders, such as intellectual disability and autism." (PMID 34184026, 2021). "Considering that TCF4 is an essential transcription factor in brain development and is linked to intellectual disability, we sought to further characterize the potential misregulation of TCF4 in HD." (PMID 34518368, 2021). "TCF4 mutations cause Pitt–Hopkins syndrome, a neurodevelopmental disorder characterized by developmental delay and intellectual disability and is highly associated with schizophrenia." (PMID 33462220, 2021). "Previous studies have revealed that the TCF4 gene is associated with many mental disorders and deficiencies, and a translocation disrupting exon 4 of TCF4 was found associated with mental retardation and suggested a high risk for SCZ." (PMID 32280673, 2020). "TCF4 mutations have been found in large-scale genotyping studies in patients with intellectual disability and autism spectrum disorder (ASD)." (PMID 32765228, 2020). "Haploinsufficiency of TCF4 causes PTHS – a rare form of intellectual disability associated with characteristic facial features and motor and speech dysfunction." (PMID 32765228, 2020). "Conversely, rare damaging TCF4 mutations cause Pitt–Hopkins syndrome and have also been found in individuals with intellectual disability (ID) and autism spectrum disorder (ASD)." (PMID 29228394, 2018). "Interestingly, in 2016, two different cases were reported of family members with mild intellectual disability carrying a hereditary TCF4 mutation." (PMID 33414364, 2021). "Furthermore, many genes that code for synaptic proteins and have been linked to autism, intellectual disability, or psychiatric diseases, are direct targets of TCF4." (PMID 32641419, 2020). "Furthermore, many genes that are mutated in SCZ, autism spectrum disorder and intellectual disability patients are TCF4 target genes." (PMID 32641419, 2020). "Usually, individuals with variants affecting exons 1 to 5 in the TCF4 gene associate mild intellectual disability (ID), between exons 5 to 8, moderate to severe ID and sometimes have some of the characteristics of PTHS, and variants starting from exon 9 to exon 20 associate a typical PTHS phenotype." (PMID 32481733, 2020). "In addition to its biological function in brain development, TCF4 is also associated with speech and language abilities, as well as intellectual disability." (PMID 30930929, 2019). "In addition to the proneural genes, a number of genes implicated in rare Mendelian forms of mental retardation were differentially expressed in TCF4 knockdown cells." (PMID 24058414, 2013). "Besides impaired emotion processing, mutations in TCF4 may lead to Pitt‐Hopkins syndrome, characterized by intellectual disabilities as well as altered brain morphology." (PMID 35796185, 2022).